EGFR (epidermal growth factor receptor)
Diseases named in the same sentence as EGFR in open-access papers (continued):
Sharing a sentence is not in itself a finding about the gene and the disease.
cancer (continued). "Gefitinib is an EGFR kinase inhibitor that disrupts signaling by blocking the EGFR kinase domain, and is therefore effective only in cancers with activating EGFR mutations." (PMID 28537895, 2017). "EGFR, which is expressed on the cell surface of normal cells and overexpressed in many cancer cells and associated with cancer cell proliferation, metastasis and survival." (PMID 28961023, 2017). "EGFR inhibition caused massive cancer cell death in 3D models expressing mutated EGFR, whereas all 2D cultures showed only highly attenuated responses." (PMID 29296175, 2017). "An irreversible ErB-family blocker, afatinib, retains its inhibitory effects on signal transduction and in vitro and in vivo cancer cell growth in tumors resistant to reversible EGFR inhibitors, such as those harboring the T790M mutation." (PMID 29228636, 2017). "Since the EGFR intron 1 CA repeat genotype is known to be associated with the gene’s transcriptional activity, the CA repeat genotype has been implicated in cancer risk and in patient clinical outcome." (PMID 28694429, 2017). "Next, to confirm the association of miR-206 with c-MET/EGFR in NRF2-silenced cancer cells, shNRF2-SKOV3 and shNRF2-A498 were transfected with the miR-206 inhibitor nucleotides." (PMID 29291022, 2017). "Gene polymorphism and mutations that lead to EGFR overexpression, over activity, or constant activation has been associated with a number of cancers." (PMID 28700691, 2017). "EGFR overexpression has been associated with cancer cell proliferation, motility, migration, and invasion in various types of tumors, including breast, lung, colon, ovarian, and brain tumors." (PMID 29291022, 2017). "Anomalous expression of TGFα or EGFR by cancer cells is associated with an aggressive phenotype and poor prognosis, also because the activation of EGFR signaling results in up-regulation of pro-angiogenic factors such as VEGF." (PMID 28906427, 2017). "Patients can access a database entitled DNA-mutation Inventory to Refine and Enhance Cancer Treatment (DIRECT) for Epidermal Growth Factor Receptor (EGFR) mutation for non-small cell lung cancer (NSCLC)." (PMID 28975082, 2017). "Our data also distinguish a different SOX2 enhancer region accessible to NFATc2 which functions not only in the presence of KRAS mutation (A549, PDCL#24) but also in EGFR mutant (HCC827) cancers." (PMID 28737489, 2017). "Sustained receptor activation occurs during chronic inflammation or upon mutation resulting from carcinogen exposure and oncogenic EGFR is linked to a number of cancer types." (PMID 27786612, 2017). "In summary, our work describes a novel mechanism by which B-Myb promotes A3B expression linked to EGFR amplification (and corresponding changes in EGFR signaling) in numerous cancer types." (PMID 28276478, 2017). "In cancer, EGFR is often mutated and, for this reason, continually activated and stimulated because of the sustained production of EGFR ligands such as EGF, TGFα, amphiregulina and heparin-binding EGF." (PMID 28906427, 2017). "Most successful examples of DNA mutations as biomarkers were found in well-studied cancer genes, such as EGFR, KRAS, and BRAF." (PMID 28984208, 2017). "The landmark IPASS trial proved the benefit of an EGFR TKI—gefitinib—in patients with EGFR-mutated cancers." (PMID 29928550, 2017). "Due to the pathogenic effects of EGFR in multiple studies, EGFR antagonism by antibodies or small-molecule inhibitors has been shown to have beneficial effects in cancer patients." (PMID 28427241, 2017). "PRL-3 has specifically been implicated in activation of acknowledged cancer progression pathways like phosphatidylinositol-3 kinase, regulating mTOR activation, Src tyrosine protein kinase, epidermal growth factor receptor (EGFR), and ERK." (PMID 29190795, 2017).
cancer (continued). "GE11 is studied as a peptide ligand, selectively recognizing EGFR for diagnostic and therapeutic purposes with respect to EGFR-overexpressing cancer cells." (PMID 29271876, 2017). "The commonly observed activation of EGFR and downstream signal transduction pathways in cancers is caused by increased ligand expression, genomic amplification of EGFR, and heterodimer formation of EGFR with other RTKs." (PMID 28978055, 2017). "Conversely, clinical implementation of EGFR inhibitors has provided important insights into the mechanisms of cancer development induced by EGFR-activating mutations." (PMID 29140271, 2017). "Although rarely mutated, EGFR is highly upregulated in many cancers with epithelial origins, including HNSCC in which EGFR upregulation is found in over 95% of the tumors." (PMID 27924064, 2017). "A reciprocal relationship between Dsg1 and neddylated EGFR was observed in a 3D carcinoma model, raising the possibility that loss of desmosomes during cancer progression unscaffolds membrane-associated CSN complexes, resulting in hyper-neddylated EGFR." (PMID 28891468, 2017). "Although NSCLC with EGFR mutation display significant responses to EGFR TKIs, cancer cells eventually become resistant to the treatment and median duration of response is about 10 to 14 months." (PMID 27431492, 2016). "Both mutation and amplification of the prototype member, EGFR, have been observed in a number of cancers." (PMID 27597943, 2016). "Non-small cell lung cancer (NSCLC) is a common and rapidly fatal cancer for which targeted therapies have been markedly effective in about 20% of patients, specifically those with EGFR mutations, ROS1 rearrangements, or EML4-ALK translocations." (PMID 26623721, 2016). "Recent advancements in molecular targeted therapy have exploited the discovery of distinct cancer subsets with epidermal growth factor receptor (EGFR) mutations and led to a major paradigm shift in the treatment of NSCLC." (PMID 27072585, 2016). "Exposure of cancer cells to EGF modulates the splicing pattern of SYK to promote the pro-survival isoform that is associated with cancer tissues in vivo and EGFR activation also induces Syk phosphorylation." (PMID 26934445, 2016). "EGFR is frequently overexpressed, mutated, or hyperactivated by excess ligand in a wide variety of cancers, including lung, brain, head and neck, and breast, among others." (PMID 27221039, 2016). "Nevertheless, in both genders, GLK protein levels were associated with cancer recurrence after adjusting for the pathologic stage, smoking behavior, alcohol behavior, and EGFR protein levels." (PMID 27203390, 2016). "Mutations of EGFR are frequently observed in various cancers, whereas inhibitors of microtubules are capable of blocking mitosis." (PMID 27117592, 2016). "Here, the authors carry out a genome-wide association study in EGFR mutant cancers and identify loci that are associated with risk of developing this molecular subtype of cancer." (PMID 27501781, 2016). "In accordance, EGFR is either amplified or mutated in majority of the cancers of epithelial origin, and therefore has been recognized as a principal target for anticancer therapy." (PMID 30370422, 2016). "EGFR and its related family members are present in various cancers and are associated with a poor prognosis for patient survival." (PMID 27153109, 2016). "EGFR mutations and overexpression have been widely linked to various types of cancers, leading the way to development of EGFR inhibitors as anticancer agents." (PMID 27287039, 2016). "Given that overexpression and/or hyper-activation of EGFR are associated with oncogenesis and poor prognosis in many cancers." (PMID 27542271, 2016). "Taken the consistent results, the present results demonstrated that the activation of EGFR was positively associated with the induction of cancer chemokines (IL-8 and CXCL-1) via NF-κB-independent pathways in type I EOC cells." (PMID 27708225, 2016).
cancer (continued). "While EGFR has been implicated as a therapeutic target for cancer therapy, EGFR pathway has also been linked to inflammation, oxidative stress, and fibrosis." (PMID 27014908, 2016). "The situation has completely changed with the appearance of target based therapy: small molecule EGFR-TKIs (e.g. gefitinib, erlotinib) have effects on cancer cells that carry the activating mutation of EGFR." (PMID 27780929, 2016). "EGFR controls cell proliferation and survival and its cellular activity is dysregulated in cancer by several mechanisms including gene mutation, gene amplification, and protein overexpression." (PMID 27732953, 2016). "Previously, many alternative splicing variants had been observed in cancer, for examples, EGFR, CD44, NER and BRCA1." (PMID 27557076, 2016). "The EGFR is overexpressed and mutated in several human cancers including the majority of cases of HNSCC." (PMID 27716204, 2016). "There is increasing recognition that epidermal growth factor receptor variant III (EGFRvIII), the most common form of mutant EGFR, is an important target for cancer therapy." (PMID 27391842, 2016). "Epidermal growth factor receptor (EGFR) is overexpressed in various types of human cancers and its expression is implicated with poor clinical prognosis." (PMID 27649234, 2016). "Different from chemotherapeutics, the EGFR-targeting drugs showed much lower side effects with significant anti-cancer efficacy in patients harboring drug-sensitive EGFR mutations." (PMID 27835586, 2016). "Plasma extracted from 171 patients with a variety of cancers was analyzed for ctDNA (54 genes and copy number variants (CNVs) in three genes (EGFR, ERBB2 and MET))." (PMID 26848768, 2016). "A signaling pathway that is frequently deregulated in human carcinomas and has been intensively explored as a therapeutic cancer target involves the activation of the epidermal growth factor receptor (EGFR) via amplification or mutation." (PMID 27248176, 2016). "EGFR mutations are commonly observed in cancers with both point mutations and large deletions observed in clinical cases." (PMID 27153091, 2016). "EGFRvIII is a functional and permanently activated mutation of the EGFR, a protein that contributes to cell growth and has been well validated as a target for cancer therapy." (PMID 26778701, 2016). "As we previously reported, amplification of oncogenes such as the epidermal growth factor receptor (EGFR) gene is accompanied by protein overexpression and can be associated with poor prognosis in human cancers." (PMID 27764170, 2016). "In cancers where EGFR is rarely mutated, high EGFR activity can still be evident, resulting in hyperactive downstream MAPK and PI3K/AKT/mTOR signaling." (PMID 27221039, 2016). "Fourth, this study didn't involve the detection of EGFR resistance mutation and molecular changes of cancer tissues." (PMID 27655708, 2016). "Increased AREG levels have been associated with enhanced response to EGFR TKIs in EGFR wild-type cancer cell lines and patient tumors." (PMID 27004400, 2016). "The occurrence of KRAS activating point mutations is reported being mutually exclusive to EGFR mutations in treatment naïve patients possible due to their overlapping pathways in the onset of cancer." (PMID 27528220, 2016). "The cancers with mutated EGFR have been suggested to have an “oncogene addiction”, serving as the basis for EGFR targeted therapies." (PMID 26623728, 2016). "In the current study, activated Peripheral Blood NK cells (PBNK) were combined with anti-EGFR mAbs to study their effect on the killing of EGFR+/- cancer cell lines, including those with RAS mutations." (PMID 27314237, 2016). "When EGFR mutation in ctDNA was the same as that detected in cancer tissue, the ctDNA was defined as major EGFR ctDNA." (PMID 27708242, 2016). "Our cytotoxicity experiment on cell lines showed that hyperthermia and cisplatin synergistically killed EGFR kinase domain mutation positive cancer cells." (PMID 26654941, 2016).
cancer (continued). "The somatic mutations leading to EGFR overexpression or over-activated have been associated with a number of cancer development, progression, angiogenesis and metastatic spread." (PMID 26918608, 2016). "It is well known that EGFR and ErbB2 have been associated with the development of numerous human cancers." (PMID 27087918, 2016). "After detection of EGFR mutations in individual patients’ cancers from biopsy samples, the EGFR‐mutant genes will be repaired or destroyed with virus‐delivered CRISPR/Cas system." (PMID 26747090, 2016). "Our work, therefore, illustrates a pathogenic positive feedback loop involving HCV, Netrin-1, and EGFR, among other factors, in association with cancer development." (PMID 27031829, 2016). "The Akt pathway is frequently up-regulated in cancer due to overexpression of receptors such as the epidermal growth factor receptor, or mutation of signalling pathway kinases resulting in inappropriate survival and proliferation." (PMID 27811956, 2016). "Several mechanisms lead to the abnormal activation of EGFR observed in various cancers, i. e., EGFR over-expression, mutation, and ligand-receptor independent stimulation." (PMID 27175782, 2016). "Between January 2008 and October 2013, 114 advanced EGFR mutations NSCLC patients who received EGFR-TKIs as first-line therapy were recruited from two cancer centers." (PMID 26624882, 2016). "Drug resistance in over 50% of cancers is caused by a mutation in the adenosine triphosphate (ATP) binding pocket of the EGFR kinase domain." (PMID 27029067, 2016). "In our study, we performed NGS, which included a panel of 483 cancer-related genes in 43 patients using tissue samples that contained EGFR exon 18–21 mutations." (PMID 27001083, 2016). "The EGFR amplification or expression of the EGFR variant 3 (EGFRviii) is generally associated with resistance to the conventional anti-cancer therapy, through potential activation of the pro-survival signaling and DNA-repair mechanisms." (PMID 30370422, 2016). "PA-mediated risk of cancer has attracted the attention of several research groups, yet any role of EGFR, a key cell growth regulator, in PA-induced cellular pathology has remained unexplored." (PMID 27287039, 2016). "MAPK1 activity has generally been reported to be associated with resistance to EGFR TKIs in cancers other than HNSCC." (PMID 27004400, 2016). "BIM polymorphism and BIM levels in treatment-naive cancers determine sensitivity to receptor kinase inhibitors, particularly EGFR and mutant B-RAF signaling pathway inhibitors, glucocorticoids, and paclitaxel." (PMID 25611383, 2015). "Mutations of EGFR lead to ligand overexpression, which has been associated with a number of cancers." (PMID 26544626, 2015). "Data on demographics, smoking history, cancer stage, histology, and EGFR/ALK mutation status were collected and analyzed." (PMID 26582178, 2015). "While mutations in KRAS, BRAF, PIK3CA, and EGFR were found in cancer types expected, there were also several instances of actionable mutations identified in diseases for which these mutations have not been well characterized." (PMID 26015395, 2015). "The proportion of cancer cells carrying mutated EGFR was calculated on the basis of the output of NGS analysis that furnishes the proportion of the mutated alleles (PMA), i.e., the number of mutated alleles over the total alleles analyzed." (PMID 25904052, 2015). "In the last decade, several investigations have demonstrated that the inter-receptor cross-talk mechanism combines the broad diversity of GPCRs with the signaling capacities of EGFR, and this association is frequently observed in human cancer." (PMID 26462152, 2015). "Overexpression of EGFR is associated with several hallmarks of cancer, including inhibition of apoptosis, sustained angiogenesis, proliferation and survival, and tissue invasion and metastasis." (PMID 25723471, 2015).
cancer (continued). "The binding potential (BP; proportional to receptor concentration) of EGFR – a cell-surface receptor associated with cancer – was estimated from kinetic modeling of targeted and untargeted NP concentrations in response to serial rinsing." (PMID 25716578, 2015). "Until recently, few studies have linked response and resistance to EGFR-targeted therapy to the status of cancer cell metabolism." (PMID 25871473, 2015). "All but one cancer sample (90%) with EGFR amplification and 7 out of 12 samples (58%) with EGFR gain had an EGFR mutation." (PMID 25719557, 2015). "It was shown that certain somatic mutations within the kinase domain of EGFR sensitize cancers to treatment with EGFR-specific tyrosine kinase inhibitors (TKIs), such as erlotinib or gefitinib." (PMID 25719557, 2015). "The purpose of this study was to clarify the relationship between the EGFR-L858R mutation and cancer cell invasion ability and to investigate the molecular mechanisms involved in the formation of MPE." (PMID 26338423, 2015). "Some studies have described the effect of saracatinib or dasatinib on cancer cell lines carrying EGFR TK variants, either wt or mutants." (PMID 26325669, 2015). "Although the NSCLC tumors carrying mutated EGFR display significant responses (as high as 80%) to EGFR-TKIs, the cancer cells eventually become resistant to the treatment and median duration of response is about 10 to 16 months." (PMID 25714021, 2015). "It is worth noticing that aggressive cancer cells that harbor KRAS or EGFR mutations secreted serglycin constitutively in elevated levels." (PMID 26581653, 2015). "Anti-EGFR therapy is becoming a standard strategy for cancer therapy; however, there are some side effects caused by anti-EGFR agents because of damage to EGFR expressing normal tissues." (PMID 25799278, 2015). "EGFR signaling pathways originate form EGFR dimerization, which produces signaling diversity and is closely associated with cancer development and malignancy." (PMID 25993617, 2015). "In the recent years, more studies have been carried out for the association between EGFR and various kinds of cancers." (PMID 25695063, 2015). "The purpose of this study was to clarify the relationship between the EGFR-L858R mutation and cancer cell invasion ability and to determine the molecular mechanisms involved in the formation of MPE." (PMID 26338423, 2015). "In the last 10 years, numerous methods with different sensitivities and specificities have been used to detect EGFR mutations in cancer samples." (PMID 25719557, 2015). "It interrupts EGFR signaling of target cells and therefore is effective only in cancer cells with mutated and overactive EGFR." (PMID 25789858, 2015). "The preliminary data demonstrated that FS-93 inhibited the proliferation of many cancer cell lines, in which EGFR mutation addicted HCC827 cells showed exquisite sensitivity." (PMID 26097875, 2015). "In a variety of human cancers, increased expression of EGFR has been identified and shown to be associated with advanced disease, development of metastases, and poor clinical prognosis in a subset of these cancers." (PMID 26338103, 2015). "EGFR, important growth factor receptor implicated in many cancers, is one of the targets for chemotherapy." (PMID 25948104, 2015). "A combination of the irreversible EGFR TKI afatinib with cetuximab was tested in a phase Ib clinical trial in advanced EGFR-mutated NSCLC cancers, which had progressed after EGFR TKI therapy." (PMID 26325669, 2015). "EGFR has been linked to Warburg effect only recently and all experiments were based on in vitro cancer cell lines." (PMID 26147004, 2015).